SIK2 (salt inducible kinase 2)
Diseases named in the same sentence as SIK2 in open-access papers (continued):
Sharing a sentence is not in itself a finding about the gene and the disease.
breast carcinoma (continued). "Overall, these data suggest SIK2 expression as a prognostic marker in breast cancer, especially for basal subtype." (PMID 29774109, 2018). "In this study, we introduce SIK2 as a novel potential tumor suppressor in breast cancer progression mediating its effects, in part, via simultaneous inhibition of Ras/ERK and PI3K/Akt signaling pathways." (PMID 29774109, 2018). "Similarly, salt-inducible kinase 2 (SIK2) is capable of regulating the stem cell phenotype of breast cancer by favoring the phosphorylation of the CK1 protein kinase and the co-receptor of the Wnt/LRP6 signaling, facilitating the Wnt/β-catenin activation." (PMID 37492224, 2023). "In contrast, SIK2 may serve as a tumor suppressor in breast cancer and pancreatic ductal adenocarcinomas." (PMID 33128264, 2021). "While most reports suggest that SIK2 is an oncogenic marker, one study in Turkey claimed that SIK2 is a potential tumor suppressor in breast cancer; SIK2 expression was reportedly reduced in tumor tissues and breast cancer cell lines compared with that in normal counterparts." (PMID 30723708, 2019). "Interestingly, in a cohort of breast cancer patient, deletion of genomic region 11q23, which includes the SIK2 gene, was reported." (PMID 29774109, 2018). "Next, we asked if SIK2 may also be downregulated in breast cancer cell lines when compared to normal cell line." (PMID 29774109, 2018). "The results confirm our in vitro findings with respect to the inverse correlation between SIK2 levels and mitotic ability of cells in vivo and support our hypothesis that SIK2 activity contributes to the inhibition of breast cancer cell proliferation." (PMID 29774109, 2018). "Here, we provide, to the best of our knowledge, the first evidence of SIK2 downregulation, its contribution to breast cancer patient survival, and its potential tumor suppressor role in breast cancer cells, which can potentially be mediated by simultaneous blockage of Ras/ERK and PI3K/Akt pathways." (PMID 29774109, 2018). "Thus, our analysis supports the notion that SIK2 expression is frequently downregulated in primary breast cancer samples and breast cancer derived cell lines." (PMID 29774109, 2018). "To establish a potential link between SIK2 expression and breast malignancies, we first investigated SIK2 expression profiles of breast cancer tissues in comparison to normal mammary gland using publicly available RNA sequencing and microarray profiling datasets." (PMID 29774109, 2018). "Furthermore, SIK2 functions as an inhibitor of migration and invasion of breast cancer cells through regulation of EMT." (PMID 29774109, 2018). "Intriguingly, two studies report that SIK2 may act as a tumor suppressor in breast cancer and PDA." (PMID 30723708, 2019). "In all breast cancer combined, high expression of LKB1, AMPK, LYK5, MARK1, MARK2, NUAK2, PAK1 (both probe sets), SIK1, SIK2, BRSK1, BRSK2, SNRK, and QSK was positively correlated with improved survival compared to low expression of these genes." (PMID 34084284, 2021). "Highly expressed SIK2 and MAD2 effectively induces PTX resistance in ovarian and breast cancer." (PMID 36006482, 2023). "Decrease of PARP enzyme activity and phosphorylation of class-IIa HDAC4/5/7 were necessary and sufficient for the synergy observed between SIK2 inhibitors and PARP inhibitors for downregulating cancer cell growth in ovarian and breast cancer cell lines and xenografts." (PMID 35642638, 2022). "Until recently, there is only one report that focused on the role of SIK2 in EMT and tumor metastasis; that report demonstrated an inhibitory effect of SIK2 on migration and invasion of breast cancer cells by blocking EMT with simultaneous blockage of Ras/ERK and PI3K/AKT pathways." (PMID 33128264, 2021). "Similarly, in overall breast cancers exposed to systemic chemotherapy we found that high expression of AMPK, SIK2, and QSK led to increases in hazard ratios compared to untreated." (PMID 34084284, 2021).
breast carcinoma (continued). "However, another study in breast cancer cells found that SIK2 expression reduced AKT phosphorylation levels, whereas depletion of SIK2 led to a substantial increase in p‐AKT levels." (PMID 33128264, 2021). "Overall, our findings suggest SIK2 as a potential tumor suppressor in the control of breast tumorigenesis, at least in part, via inhibiting PI3K/Akt and Ras/ERK signaling cascades simultaneously and a novel prognostic marker, especially in basal subtypes of breast cancer." (PMID 29774109, 2018). "Because knockdown of AKT expression by RNAi was incomplete, it was not possible to rule out that SIK2 inhibition of AKT signaling might contribute to the enhancement of PARP inhibitor sensitivity in ovarian and breast cancers through a class-IIa HDACs/MEF2D–independent pathway." (PMID 35642638, 2022).
Obesity (11 papers, 2016 to 2025). Accumulation of substantial excess body fat. "However, transgenic mice that express a constitutively active SIK2 S587A mutation in BAT are prone to diet-induced obesity." (PMID 40384110, 2025). "We presumed that the reduced low level of Calr detected in the secretome of SIK2-deficient POMC neurons during the early ER stress response may interfere with the proper folding of App in relation to the pathogenesis of obesity and related diseases." (PMID 39329749, 2024). "Based on these results, modulation of p300 activity by SIK2 could serve as an attractive approach to treat obesity and type 2 diabetes-associated liver dyslipidemia." (PMID 26983400, 2016). "We proposed an unprecedented regulatory role for SIK2 in the homeostatic control of obesity-related secreted proteins within physiological boundaries in response to the early phase of ER stress conditions." (PMID 39329749, 2024). "Previously, we have shown that SIK2 is downregulated in adipose tissue of individuals with obesity and insulin resistance." (PMID 37386070, 2023). "In future studies it would be interesting to address if low adipose tissue SIK2 expression in obesity and insulin resistance is indeed a result of low-grade inflammation and the presence of elevated TNFα." (PMID 37386070, 2023). "Together, this supports a role for SIK2 in protecting against obesity-induced insulin resistance, particularly at the adipose-tissue level." (PMID 36731029, 2023). "In contrast to what was previously reported in obese mice, we found that SIK2 expression (mRNA and protein) and activity in adipose tissue and adipocytes were downregulated in human obesity." (PMID 27807598, 2017). "Based on the observation that SIK2 was most distinctly affected in human obesity, we chose to mainly focus our further studies on this isoform." (PMID 27807598, 2017). "The mechanisms by which this sustained SIK2 activity leads to diet-induced obesity might involve a coordinated alteration in insulin action, glucose uptake, and lipogenesis in the adipose tissue." (PMID 40384110, 2025). "Granulin, a marker of chronic inflammation associated with insulin resistance, obesity, and type 2 diabetes mellitus, and its expression profile in the POMC secretome also obeyed the regulatory constraint imposed by a gatekeeper function of SIK2." (PMID 39329749, 2024). "Since exogenous Gdf15 injection ameliorated the obesity phenotype in obese animal models, therapeutic strategies targeting Gdf15 or its upstream regulator SIK2 in POMC neurons of the obese human brain will require the identification of differences in the Gdf15-GFRAL axis between the two species." (PMID 39329749, 2024). "It is thus possible that downregulation of SIK2 in obesity could contribute to the development of obesity-induced insulin resistance." (PMID 37386070, 2023). "SIK2 levels are regulated by the adipogenic factor C/EBPα, whose expression is reduced in obesity." (PMID 34686752, 2021). "Indeed, SIK2 expression and function are inversely correlated with insulin resistance and obesity in humans." (PMID 34686752, 2021). "Mice with global deficiency of SIK2 displayed no weight phenotype, arguing against a causal relationship between SIK2 downregulation and obesity." (PMID 27807598, 2017). "SIK2-dependent regulation of p300 function could be important for the modulation of fatty acid oxidation and ketogenesis in obesity and insulin-resistance states." (PMID 26983400, 2016). "In humans, studies have shown that the expression and activity of SIK2 and SIK3 are downregulated in the adipose tissue of individuals with obesity." (PMID 40384110, 2025). "Salt-inducible kinase 2 (SIK2) is highly expressed in white adipocytes, but downregulated in individuals with obesity and insulin resistance." (PMID 37386070, 2023). "A critical question is how the reduced SIK2 and SIK3 expression in obesity impacts adipose tissue physiology." (PMID 27807598, 2017).
Obesity (continued). "In summary, we have demonstrated that SIK2 and SIK3 are downregulated in human obesity and insulin resistance." (PMID 27807598, 2017). "SIK2 suppresses the inflammatory content of the POMC secretome primarily in the early phase of the ER stress response, parallel to its effect on two other groups, including obesity and feeding behavior and axon guidance and neurite outgrowth." (PMID 39329749, 2024). "Moreover, a previous study described increased expression and activity of SIK2 in white adipose tissue (WAT) from obese db/db mice, suggesting a role for SIK2 in obesity and diabetes." (PMID 27807598, 2017).
Insulin resistance (8 papers, 2017 to 2024). Increased resistance towards insulin, that is, diminished effectiveness of insulin in reducing blood glucose levels. "SIK2 is also negatively associated with in vivo insulin resistance (HOMA-IR), independently of BMI and age." (PMID 27807598, 2017). "Of interest, SIK2 mRNA levels negatively correlated with in vivo insulin resistance, while its protein and kinase activity negatively correlated with body mass index." (PMID 36731029, 2023). "Increased knowledge about inflammation-induced downregulation of SIK2 could ultimately be used to develop strategies for the reinstalment of SIK2 expression in insulin resistance." (PMID 37386070, 2023). "We concluded that insulin resistance induced by high salt intake in adipocytes might be related to SIK2-induced RAAS activation." (PMID 30621146, 2019). "In line with this, Sik2-/- mice showed some degree of insulin resistance in their adipose tissue." (PMID 27807598, 2017). "Furthermore, SIK2 displayed a strong negative association with in vivo insulin resistance, measured by HOMA-IR (r = −0.76, p < 0.001)." (PMID 27807598, 2017). "SIK2 phosphorylates p35 priming for the ubiquitin ligase PJA2, which is followed by its proteasome-mediated degradation, which leads to insulin resistance (IR), which results from chronic insulin exposure." (PMID 33923622, 2021).
triple-negative breast carcinoma (8 papers, 2018 to 2026). An invasive breast carcinoma which is negative for expression of estrogen receptor (ER), progesterone receptor (PR), and human epidermal growth factor receptor 2 (HER2). "MYBL2-induced PITPNA antisense RNA 1 (PITPNA-AS1) upregulates salt-inducible kinase 2 (SIK2) to exert oncogenic functions in triple-negative breast cancer." (PMID 35341461, 2022). "Here, we showed that SIK2 inhibitors sensitized ovarian and triple-negative breast cancer (TNBC) cells and xenografts to PARP inhibitors." (PMID 35642638, 2022). "Immunostaining of patient tumors revealed that SIK2 protein level is frequently downregulated in invasive mammary carcinomas and negatively correlated with the mitotic activity of the cells in triple negative breast cancers and hormone positive tumors." (PMID 29774109, 2018). "In triple-negative breast cancer, PITPNA-AS1 upregulates SIK2 to exert oncogenic function through miR-520d-5p and DDX54." (PMID 38100482, 2023).
serous ovarian cancer (7 papers, 2015 to 2023). "One of the key players in the metastasis in the tissues (omentum and adipocyte) of the ovary that leads to HGSO (high-grade serous ovarian cancer) is the salt inducible kinase 2 (SIK2)." (PMID 37845675, 2023). "Thereafter, we examined if the expression levels of SIK2 and MYLK‐pS343 were associated with overall survival of FIGO stage III‐IV serous ovarian cancer patients." (PMID 35278271, 2022). "SIK2 is overexpressed in 30% of ovarian cancers, correlating with poor prognosis in patients with high-grade serous ovarian carcinomas." (PMID 33503955, 2021). "SIK2 has been reported to be overexpressed in high-grade serous ovarian cancer in which it functions as a centrosome kinase during cell cycle progression." (PMID 31762812, 2019). "For example, salt inducible kinase 2 (SIK2) is overexpressed in high-grade serous ovarian cancer and has been shown to function in cell division through its regulation of mitotic spindle formation by phosphorylating proteins of the centrosome." (PMID 26068970, 2015). "Among patients with high-grade serous ovarian carcinoma, SIK2 was found to be significantly overexpressed in omental metastatic tumors, with the highest SIK2 level observed at the interface between cancer cells and adipocytes, compared with the level in the corresponding primary tumor." (PMID 30568223, 2019).
depression (6 papers, 2020 to 2023). "In addition to PPARα, there are a lot of other proteins that not only control BDNF biosynthesis and neuroplasticity but also are implicated in depression, such as salt-inducible kinase 2, glycogen synthase kinase 3β and mammalian target of rapamycin." (PMID 34211395, 2021). "Chronic social defeat-induced stress (CSDS) and chronic mild stress (CMS) are both used to model depression in mice and induced SIK2 in the hippocampus and prefrontal cortex and, in agreement, also reduced nuclear CRTC1." (PMID 36731029, 2023). "Conversely, AAV-short hairpin RNA (shRNA)-mediated knockdown of hippocampal SIK2 or genetic knockout of Sik2 protect mice against both chronic stress models of depression with antidepressant-like effects that require the downstream CRTC1-CREB-BDNF pathway." (PMID 35242012, 2022). "In a chronic stress-induced depression model in mice, the levels of salt-inducible kinase 2, which is a kinase of CRTC1, was increased in the hippocampus, resulting in inhibition of CRTC1/CREB-regulated BDNF expression." (PMID 34977362, 2021). "In 2019, we have reported that chronic stress-induced depression was accompanied by increased SIK2 expression and decreased nuclear CRTC1 translocation and CRTC1-CREB binding in the hippocampus." (PMID 33519490, 2020). "Overexpression of SIK2 in the hippocampus induced depression-like behaviors, accompanied by attenuated BDNF signaling and neurogenesis, while knockdown of SIK2 produced antidepressant-like effects." (PMID 36731029, 2023). "ARN-3236, a selective inhibitor of SIK2, induced significant antidepressant-like effects in both the CSDS and CUMS models of depression by acting on the hippocampal CRTC1-CREB-BDNF pathway and adult hippocampal neurogenesis." (PMID 35242012, 2022). "Hippocampal SIK2 has been reported to be up-regulated and CRTC1-CREB signalling suppressed in two different mouse models of depression (chronic social defeat stress (CSDS) and chronic unpredictable mild stress (CUMS))." (PMID 33861845, 2021). "Moreover, the overexpression of SIK2 in the hippocampus of mice induced depressive-like behaviour, while the knock-down or KO of SIK2 in the hippocampus prevented mice from displaying such behaviour when challenged with either the CUMS or CSDS models of depression." (PMID 33861845, 2021).
pulmonary fibrosis (6 papers, 2020 to 2025). Chronic progressive interstitial lung disorder characterized by the replacement of the lung tissue by connective tissue, leading to progressive dyspnea, respiratory failure, or right heart failure. "Given that lung fibrosis in mice has been linked to increased polarization of macrophages to an IL-4-induced “M2a” phenotype, the effect of the SIK2 kinase-inactive knockin was tested on IL-4 and LPS-induced markers on macrophages." (PMID 36309093, 2022). "Interestingly, this was mirrored by the effects of SIK2 kinase-inactive knockin mutations in bleomycin-induced lung fibrosis." (PMID 36309093, 2022). "This study elucidates the mechanistic role of salt-inducible kinase 2 (SIK2) as a pivotal contributor to the progression of pulmonary fibrosis, primarily through the activation of glycolysis." (PMID 40868174, 2025). "A selective SIK2 inhibitor ARN-3236 restricts fibroblasts differentiation and ECM gene expression in human fetal lung fibroblasts and attenuates bleomycin-induced pulmonary fibrosis in mice, supporting as pathological role for SIK2 in pulmonary fibrosis." (PMID 39081779, 2024). "Taken together, these results indicated that SIK2 and the phosphorylation of CRTC2 regulated by SIK2 is involved in the progression of pulmonary fibrosis." (PMID 35410283, 2022). "Our results elucidate a previously unexplored role of SIK2 in pulmonary fibrosis through modulation of CRTC2/ CREB signaling pathway." (PMID 35410283, 2022). "When combined, these results suggested that inhibition of SIK2 protected against BLM-induced pulmonary fibrosis in mice." (PMID 35410283, 2022). "Together, the data presented here identify SIK2 as a target of a clinically approved antifibrotic drug and show that the SIK2 kinase-inactive knockin mouse is protected in a bleomycin-induced mouse model for lung fibrosis." (PMID 36309093, 2022). "In conclusion, our results elucidated a previously unexplored role of SIK2 in pulmonary fibrosis, and identified SIK2 as a new target for anti-fibrosis medicines." (PMID 35410283, 2022). "Inhibition of SIK2 significantly attenuated bleomycin-induced pulmonary fibrosis by promoting dephosphorylation and nuclear translocation of CRTC2 and consequently activating the CREB anti-fibrotic pathway." (PMID 35410283, 2022). "We show that SIK2 kinase-inactive knockin mice are protected in a bleomycin-induced lung fibrosis model." (PMID 36309093, 2022). "Consistently, dasatinib, a dual tyrosine kinase/SIK2 inhibitor, has been identified as an anti-fibrotic agent in mice with pulmonary fibrosis." (PMID 35410283, 2022). "We show here that loss of SIK2 activity protects against bleomycin-induced lung fibrosis in mice, and that the clinically approved IPF drug nintedanib is a potent inhibitor of SIK2." (PMID 36309093, 2022). "Further work will therefore be required to determine the targets of SIK2 during the development of lung fibrosis." (PMID 36309093, 2022). "Together, these results suggest that SIK2 is a potential drug target for the treatment of lung fibrosis." (PMID 36309093, 2022). "Inactivation of SIK2 alleviated BLM-induced lung fibrosis in mice and suppressed fibroblast activation and differentiation." (PMID 35410283, 2022). "The SIK2 (salt-inducible kinase-2) inhibitor ARN-3236 was recently reported to attenuate bleomycin-induced pulmonary fibrosis in mice." (PMID 36499337, 2022). "Therefore, for the first time we report that SIK2 acts as a pro-fibrotic factor in the progression of pulmonary fibrosis." (PMID 35410283, 2022). "Collectively, these studies demonstrated that inhibition of SIK2 can alleviate pulmonary fibrosis." (PMID 35410283, 2022). "So far, the function of SIK2 under pulmonary fibrosis conditions remains undefined." (PMID 35410283, 2022). "In the current study, we examined whether inactivation of SIK2 could attenuate pulmonary fibrosis." (PMID 35410283, 2022).